TYRO3 (TYRO3 protein tyrosine kinase)
Diseases named in the same sentence as TYRO3 in open-access papers (continued):
Sharing a sentence is not in itself a finding about the gene and the disease.
Arthritis (3 papers, 2018 to 2023). Inflammation of a joint. "More specifically, we demonstrated that Axl or Mertk knockout enhances the severity of arthritis, while selective deficiency of Tyro3 in contrast attenuates arthritis." (PMID 37537628, 2023). "Here, to investigate TAMs in an inflammatory arthritis model, antibody-induced arthritis in single TAM-deficient mice (Tyro3- KO, Axl-KO, Mertk-KO) was induced by K/BxN serum injection." (PMID 37537628, 2023). "Although TAM receptors are able to regulate the innate immune response, it is unclear how Axl, Mertk, and Tyro3 regulate innate immune cells affecting the severity of arthritis." (PMID 37537628, 2023). "Compared with littermate control mice, Axl−/− and Mertk−/− mice developed more severe antibody-induced arthritis, while in contrast, Tyro3−/− mice showed diminished joint inflammation." (PMID 37537628, 2023). "In contrast with these results, data about the role of Tyro3 in arthritis showed that its activation is detrimental for the joints as it mediates synovial hypertrophy and increases the erosive burden." (PMID 32051695, 2020). "In this study, we performed a comparison study of the phenotypes of single TAM gene deficient mice in the K/BxN serum transfer-induced arthritis (K/BxN-STIA) model and inveistigated the potential mechanism by which Tyro3, Axl, and Mertk have distinct or overlapping functions in RA." (PMID 37537628, 2023). "In contrast with the protective role hypothesised for Axl and Mer, induction of arthritis in Tyro3−/− mice revealed that the third member of TAMs might instead play a proarthritic role." (PMID 32051695, 2020). "In this manuscript, we describe that mice deficient for Tyro3/Axl/Mertk do not develop clinical characteristics of arthritis until the age of 52 weeks." (PMID 30335822, 2018). "However, another study showed that Tyro3 supports arthritis." (PMID 37537628, 2023). "To better understand the function of TAM receptors in the pathogenesis of autoantibody-induced arthritis, we examined the phenotype of knockout mice lacking Tyro3, Axl or Mertk in the K/BxN-STIA model." (PMID 37537628, 2023). "Taken together, the differential cytokine expression levels in mice lacking Axl, Mertk and Tyro3 are consistent with their phenotypes in arthritis, suggesting that TAMs differentially regulate antibody-induced inflammatory responses that contribute to the development of arthritis." (PMID 37537628, 2023).
chronic lymphocytic leukemia (3 papers, 2016 to 2018). "TYRO3 was also expressed in B and T-cell acute lymphoblastic leukemia (ALL) cell lines and chronic lymphocytic leukemia patient samples." (PMID 30501104, 2018). "Another small molecule named TP-0903 induces apoptosis in primary chronic lymphocytic leukemia (CLL) B-cells by targeting Axl without inhibiting phosphorylated Tyro3, overcoming bone marrow stromal cell protection of the leukemic B-cells." (PMID 30322068, 2018).
Flavivirus Infections (3 papers, 2019 to 2023). Infections with viruses of the genus FLAVIVIRUS, family FLAVIVIRIDAE. "A previous study reported the involvement of receptor TKs (RTKs) belonging to the Tyro-3, Axl, and Mer family of RTKs in flavivirus infection." (PMID 33371476, 2020). "TAM family and TIM family genes, mainly including AXL, TYRO3, MERTK and TIM-1, were suggested as putative host factors in flavivirus infection of human host cells." (PMID 37684223, 2023). "Additionally, some investigations have also suggested that the T-cell immunoglobulin and mucin domain (TIM) and TYRO3, AXL and MER (TAM) can enhance flavivirus infection by binding to PtdSer on the virion surface rather than E glycoprotein." (PMID 31718685, 2019).
glioblastoma (3 papers, 2018 to 2025). The most malignant astrocytic tumor (WHO grade IV). "The ability of foretinib to inhibit the TAM family members of receptor tyrosine kinases (Tyro3, Axl, and MerTK) hindered the survival, proliferation, and migration of glioblastoma cell lines in vitro and reduced glioblastoma tumor growth in a subcutaneous mouse model." (PMID 35743016, 2022).
head and neck cancer (3 papers, 2017 to 2020). A primary or metastatic malignant neoplasm affecting the head and neck. "In SCC-25 head and neck cancer cells expressing both Tyro3 and Axl, Western blotting showed that both natural TAM ligands ProS1 and Gas6 rapidly stimulated Tyro3 and Erk kinase phosphorylation, with ProS1 eliciting a greater effect." (PMID 31766614, 2019). "Having identified cancer cell lines with Tyro3 expression, we selected SCC-25 head and neck carcinoma cells for further study as these cells showed a consistent response to ligand stimulation and with less potential influence of the other TAM receptors." (PMID 31766614, 2019). "In keeping with previous studies which identified high AXL expression and AXL-mediated oncogenic properties in OSCC and head and neck cancers, we found AXL to be highly expressed in our cell lines, whereas TYRO3 and MERTK levels were barely detectable." (PMID 28118606, 2017).
leiomyosarcoma (3 papers, 2018 to 2025). An uncommon, aggressive malignant smooth muscle neoplasm, usually occurring in post-menopausal women. "In leiomyosarcoma patients, especially those whom develop metastasis, express higher levels of Tyro3 and Gas6, and crizotinib and foretinib showed effective antitumor activity in leiomyosarcoma through Tyro3 and Axl deactivation." (PMID 36059952, 2022).
lung carcinoma (3 papers, 2016 to 2024). "It was also reported that EGCG could reverse cisplatin resistance through down regulating Axl and Tyro3 in human lung cancer cells." (PMID 27391608, 2016). "Moreover, AXL and the other TAM receptors (TYRO3 and MERTK) have been reported as key mediator of chemoresistance in neuroblastoma through induction of EMT and in lung cancer through the regulation of mitogen-activated protein kinase (MAPK) and FAS signaling pathways." (PMID 34745951, 2021).
lupus (3 papers, 2014 to 2020). "The expression of Tyro3 was strongly associated with the expression of Mer in the CD4+ T lymphocytes of lupus patients." (PMID 24650765, 2014). "Though Tyro3 expression and function primarily associate with the central nervous system, we will review the published Tyro3 studies under the scope of immune regulation suggesting a function in the pathogenesis/therapeutics in lupus." (PMID 31360267, 2019). "Surprisingly, a small but significant increase in Tyro3 expression was present on CD4+ T cells in lupus patients." (PMID 24650765, 2014). "An increased Mer and Tyro3 expression on CD4+ cells was noted in lupus patients compared with normal control subjects." (PMID 24650765, 2014). "Mer levels correlated with Tyro3 levels on the surface of CD4+ T cells in lupus patients." (PMID 24650765, 2014). "We found that Tyro3 and Mer are expressed on CD4+ T cells in some individuals with lupus." (PMID 24650765, 2014).
atherosclerosis (2 papers, 2016 to 2024). A disease characterized by the build-up of fatty material and calcium deposition in the arterial wall resulting in partial or complete occlusion of the arterial lumen. "AXL, a member of the TAM (Tyro3, Axl, MerTK) family of receptors, plays important roles in cell survival, clearance of dead cells (efferocytosis), and suppression of inflammation, which are processes that critically influence atherosclerosis progression." (PMID 27958361, 2016). "The Tyro3, Axl, and Mer (TAM) family of receptor tyrosine kinases is involved in the amplification or resolution of atherosclerosis pathology and other cardiovascular pathology." (PMID 39684449, 2024). "Our data showing that Axl deficiency in bone marrow-derived cells does not affect the most important parameters of advanced atherosclerosis is quite surprising and cannot be explained by compensatory up-regulation of MerTK or Tyro3." (PMID 27958361, 2016).
bladder tumor (2 papers, 2019 to 2022). "We have previously demonstrated that TYRO3 is overexpressed in 50% of BCa and that TYRO3 overexpression conferred a TYRO3-dependence to bladder tumor cells both in vitro and in vivo." (PMID 35955805, 2022). "Recently, we demonstrated that TYRO3 is upregulated in 50% of MIBCs and that TYRO3 overexpression conferred a TYRO3-dependance to bladder tumor cells." (PMID 35955805, 2022). "Accordingly, TYRO3-dependent bladder tumour cells were sensitive to pharmacological treatment with two pan-TAM inhibitors." (PMID 30765874, 2019). "Consistent with our results for human bladder tumours, TYRO3 was the TAM receptor most frequently expressed in UBC cell lines (in 21 out of 25 cell lines), followed by AXL (13/25) and MERTK (7/25)." (PMID 30765874, 2019). "Consistent with this general higher level of expression of TYRO3 in bladder tumours compared to normal samples, TYRO3 expression was detected in most of the UBC cell lines, whereas AXL and MERTK had more heterogeneous expression patterns in UBC cell lines." (PMID 30765874, 2019). "Overall, these results suggest that TYRO3 may play a role in bladder tumours." (PMID 30765874, 2019). "No alteration of the TYRO3 copy number was detected (data not shown), and the mechanisms increasing the expression of TYRO3 in bladder tumour cells remain to be determined." (PMID 30765874, 2019).
carotid atherosclerosis (2 papers, 2019 to 2024). A thickening and loss of elasticity of the walls of carotid arteries that occur with formation of atherosclerotic plaques. "Apart from a study showing an association between Tyro3 and MerTK variants and carotid atherosclerosis, the net contribution of Tyro3 to CVD has not been addressed to date." (PMID 30980657, 2019).
Cirrhosis (2 papers, 2020 to 2022). A chronic disorder of the liver in which liver tissue becomes scarred and is partially replaced by regenerative nodules and fibrotic tissue resulting in loss of liver function. "In CLD with and without compensated cirrhosis, however, MERTK and TYRO3 expressions were sparse." (PMID 31822557, 2020).
colorectal tumor (2 papers, 2016 to 2019). "Strikingly, but as previously observed in colorectal tumour cells, TYRO3 staining was mainly detected in the cytoplasm of tumour cells and also at the plasma membrane." (PMID 30765874, 2019). "In summary Tyro3 is higher expressed in primary human colorectal tumors and liver metastases compared to normal tissues, whereas Gas6 is only higher expressed in liver metastases." (PMID 27486820, 2016). "All human colorectal tumor cell lines expressed the TAM receptors Axl, Tyro3 and Mer." (PMID 27486820, 2016).
experimental autoimmune encephalomyelitis (2 papers, 2020 to 2025). An autoimmune demyelinating disease of the central nervous system that is produced experimentally in animals by the injection of homogenized brain or spinal cord in Freund's adjuvant. "During experimental autoimmune encephalomyelitis (EAE), the mRNA expression of MerTK, Gas6, and Axl significantly increase, whereas Tyro3 and ProS1 remain unchanged." (PMID 33121494, 2020).
frontotemporal lobar degeneration (2 papers, 2024). "This localization is also consistent with the Tyro3 activation of post-synaptic protein kinase C and other kinases that has been observed in a mouse model of frontotemporal lobar degeneration." (PMID 38410160, 2024).
infertile (2 papers, 2014 to 2024). "Sertoli cells express all three TAM receptors and both ligands, and Tyro3/Axl/Mer triple mouse mutants are infertile due to the toxic accumulation of ACs." (PMID 25265470, 2014).
lymph node metastasis (2 papers, 2020 to 2023). "Then, multivariate analysis using these four independent risk factors demonstrated that depth of tumor invasion, lymph node metastasis, and TYRO3 expression significantly affected survival (P < 0.05)." (PMID 37116196, 2023). "The aberrant TYRO3 expression is closely associated with neural invasion, lymph node metastasis, and TNM stage, thereby predicting poor prognosis." (PMID 37116196, 2023). "The results revealed that neural invasion, depth of tumor invasion, lymph node metastasis, and TYRO3 expression were independent risk factors (P < 0.05)." (PMID 37116196, 2023). "High TYRO3 expression was associated with neural invasion (P = 0.019), lymph node metastasis (P < 0.001), and TNM stage (P < 0.001)." (PMID 37116196, 2023). "Neural invasion, depth of tumor invasion, lymph node metastasis, and TYRO3 expression were included using Cox univariate analysis." (PMID 37116196, 2023). "Next, an analysis of the clinicopathological features of 110 GC patients showed that TYRO3 was significantly related to tumor size, T stage, pTNM stage, and lymph node metastasis (P < 0.05), suggesting that TYRO3 might play a key role in GC progression and metastasis." (PMID 32018224, 2020). "However, no statistical correlation could be observed between the TYRO3 expression level and survival prognosis in patients having positive neural invasion or negative lymph node metastasis (P > 0.05)." (PMID 37116196, 2023).
metastatic tumor (2 papers, 2022 to 2025). "TYRO3 amplification showed a similar pattern, being more frequent in primary tumors (65% primary vs. 3% metastatic tumor; p < 0.001)." (PMID 41373665, 2025). "An analysis of activated RTKs in TH tumor lysates revealed a striking dichotomy between localized and metastatic tumors with a switch from EGFR to activated TYRO3 in 57% of metastatic cases." (PMID 36230684, 2022).
periodontitis (2 papers, 2019 to 2025). An acute or chronic inflammatory process that affects the tissues that surround and support the teeth. "In periodontitis patients, elevated Pros1 and decreased Tyro3 were detected in inflamed gingiva, while the expression of Gas6, Axl and Mertk was similar to that of healthy control." (PMID 30729671, 2019). "We detected higher Pros1 but lower Tyro3 levels in inflamed gingival specimens of periodontitis patients compared with healthy controls." (PMID 30729671, 2019). "While Gas6, Axl and Mertk were detected at similar levels in periodontitis and control gingiva, Pros1 was found to be up‐regulated and Tyro3 down‐regulated in periodontitis specimens compared with controls." (PMID 30729671, 2019). "The aim of the study was to clarify the specific role of Pros1/Tyro3 axis in regulating oral inflammatory disease such as periodontitis." (PMID 30729671, 2019). "The TAM receptors Tyro3, Axl and Mertk and their ligands Gas6 and Pros1 were detected by qRT‐PCR in gingival tissues of patients with chronic periodontitis as well as healthy controls with non‐inflamed gingiva." (PMID 30729671, 2019). "Based on these data, we speculated that the Pros1/Tyro3 signalling may be the main TAM signalling involved in the development of periodontitis in humans." (PMID 30729671, 2019). "Supporting these findings, AXL, TYRO3, and GAS6 were the most accurate in differentiating between periodontally healthy/gingivitis and periodontitis, including mild or severe periodontitis (area under the curve [AUC] ranging from 0.72 to 0.89)." (PMID 41187004, 2025). "We next assessed Pros1, Tyro3 and RNAKL levels in periodontal tissues of periodontitis and sham rats." (PMID 30729671, 2019).
adenoma (1 paper, 2015). A neoplasm arising from the epithelium. "In the case of TYRO3, a significant increase in expression was observed in both carcinomas (compared to adenomas), and in samples with 13q gain (compared to tumours without 13q gain)." (PMID 26148070, 2015).
allergic asthma (1 paper, 2017). A asthma with a basis in a pathological type I hypersensitivity reaction. "Loss of Tyro3 exacerbated allergic asthma symptoms in a mouse model of house dust mite-induced airways inflammation." (PMID 28727830, 2017).
allergic reactions (1 paper, 2018). "Importantly, AXL impinges on cell motility and invasion compared to TYRO3 and MERTK, while TYRO3 acts as an inhibitor of type 2 immunity during allergic reactions." (PMID 30140167, 2018).
Alzheimer disease (1 paper, 2022). A progressive, neurodegenerative disease characterized by loss of function and death of nerve cells in several areas of the brain leading to loss of cognitive function such as memory and language. "The TAM (Tyro3, Axl, Mertk) family of receptor tyrosine kinases has been well studied for their roles in cancer biology and autoimmune disease, and a number of studies implicate a role for these receptors in the pathogenesis of Alzheimer’s disease." (PMID 35130912, 2022).
anaplastic astrocytoma (1 paper, 2024).
Anxiety (1 paper, 2024). Intense feelings of nervousness, tension, or panic often arise in response to interpersonal stresses. "Prior to carrying out these assays, we first used continuous video monitoring in open fields to ascertain that both overall mouse locomotion and anxiety behavior were unaffected by the mutation of Tyro3." (PMID 38410160, 2024).
Aortic dissection (1 paper, 2024). Aortic dissection refers to a tear in the intimal layer of the aorta causing a separation between the intima and the medial layers of the aorta. "Additionally, SR-A1 influences efferocytosis by activating the TYRO3 protein tyrosine kinase (TYRO3) signaling in macrophages, thereby contributing to the development of aortic dissection induced by beta-aminopropionitrile (BAPN)." (PMID 38807379, 2024).
Ataxia (1 paper, 2017). Ataxia refers to impaired coordination of voluntary muscle movement. "Notably, all anx/anx mice transgenic for Tyro3-GFP or HuTyro3 showed mild or no neurobiological anx-related behaviors such as ataxia, shaking and headweaving at P21, and survived at least until P35, as shown for all Tyro3-GFP and HuTyro3 transgenic lines (P<0.01)." (PMID 28093506, 2017).
choroideremia (1 paper, 2025). Choroideremia (CHM) is an X-linked chorioretinal dystrophy characterized by progressive degeneration of the choroid, retinal pigment epithelium (RPE) and retina. "Together, these findings highlight interesting similarities between choroideremia mouse models and mouse models of Mertk-associated RP (Mertk−/−V1 and Mertk−/−V2;Tyro3−/−V2)." (PMID 40332248, 2025).
chronic hepatitis (1 paper, 2013). An active inflammatory process affecting the liver for more than six months. "Tyro3−/−Axl−/−Mer−/− triple mutant (TAM−/−) mice exhibited chronic hepatitis, manifested by progressive appearance of interface hepatitis, immune cell infiltrations and elevated inflammatory cytokine levels in the liver." (PMID 23799121, 2013).
diabetic kidney disease (1 paper, 2023). Progressive kidney disorder caused by vascular damage to the glomerular capillaries, in patients with diabetes mellitus. "Of note are the TYRO3 (tyrosine-protein kinase receptor), DLK1 (protein delta homologue 1) and CTSH (cathepsin H) proteins, which are significantly associated with diabetic kidney disease (DKD)." (PMID 36349687, 2023).
endometriosis (1 paper, 2008). The growth of functional endometrial tissue in anatomic sites outside the uterine body. "AXL, a member of Tyro3/AXL/Mer (TAM) receptor tyrosine kinase (RTK) family, was shown to be upregulated in endometriosis by SAGE and IHC in the present study." (PMID 19055724, 2008).
epilepsy (1 paper, 2024). A brain disorder characterized by episodes of abnormally increased neuronal discharge resulting in transient episodes of sensory or motor neurological dysfunction, or psychic dysfunction. "Conversely, an increase in the expression levels of SLIT and NTRK-like family, member 1 (Slitrk1), TYRO3 protein tyrosine kinase 3 (Tyro3), epilepsy, progressive myoclonic epilepsy, type 2 gene alpha (Epm2a), fucosyl-transferase 9 (Fut9), immunoglobulin superfamily, member 9B (Igsf9b) was observed." (PMID 38535448, 2024).